CD5 (CD5 molecule)
Diseases named in the same sentence as CD5 in open-access papers (continued):
Sharing a sentence is not in itself a finding about the gene and the disease.
type 1 diabetes (5 papers, 2017 to 2025). "In this regard, it is of interest that CD5 has been identified as a candidate gene for a risk variant associated with Crohn’s disease, a disease that shares genetic risk with type 1 diabetes, the main trait of the NOD mouse model." (PMID 35720357, 2022). "Fas ligand drives insulitis in the non-obese diabetic mouse model of type 1 diabetes (T1D) and negatively regulates IL-10-producing (IL-10pos) CD5+ B cells in pancreata." (PMID 28439273, 2017).
AIDS (4 papers, 2005 to 2025). A syndrome resulting from the acquired deficiency of cellular immunity caused by the human immunodeficiency virus (HIV). "HIV also frequently integrates into lymphocyte activation genes, such as CD5, IL7R, STAT5B, TNFAIP3, and MALT1, which are actively transcribed during immune activation, with higher integration rates in the AIDS group." (PMID 39788938, 2025).
allergic disease (4 papers, 2005 to 2021). An immune response that occurs following re-exposure to an innocuous antigen, and that requires the presence of existing antibodies against that antigen. "A high proportion of CD5+ B cells has previously been shown to be associated with subsequent allergy development, while a high proportion of CD4+ T cells having the FOXP3+CD25high phenotype is associated with a high risk of subsequent sensitization to common environmental allergens." (PMID 33007868, 2020). "Higher levels of CD5+ B-cells have previously been shown to lead to higher allergy incidence and are a sign of an immature immune system." (PMID 34135462, 2021). "Maternal intake of fatty fish, shellfish, and total seafood also correlated negatively with the population of immature CD5+ B cells, which is a cell population that we have previously found to be positively related to allergy development." (PMID 33007868, 2020). "However, as relatively little is known about the role of CD5 in human T cell tolerance, further investigations are required to establish the relevance of our finding in allergic disease." (PMID 15783262, 2005).
Crohn disease (4 papers, 2018 to 2022). A gastrointestinal disorder characterized by chronic inflammation involving all layers of the intestinal wall, noncaseating granulomas affecting the intestinal wall and regional lymph nodes, and transmural fibrosis. "Through network analysis, we can introduce IL-7, GATA3, TXN, ETS-1, CCR7, CD28, and CD5 as Crohn’s disease-related critical genes and possible biomarker panel." (PMID 33585004, 2020). "Among the 81 queried DEGs related to Crohn’s disease, 7 genes (IL-7, GATA3, CD28, CD5, TXN, ETS-1, and CCR7) were introduced as dysregulated genes." (PMID 33585004, 2020).
EATL type I (4 papers, 2012 to 2025). "An inflammatory background is absent, and necrosis is usually less evident than in classical EATL type I. Immunohistochemically, the tumor cells are CD3+, CD4-, CD5-, CD7+, CD8−/+, CD103+, TCRβ+/−, and contain cytotoxic granule associated proteins." (PMID 23217032, 2012).
endometriosis (4 papers, 2022 to 2024). The growth of functional endometrial tissue in anatomic sites outside the uterine body. "Our results are overall consistent with the findings obtained in adult patients: adolescents with endometriosis also reveal a decrease in total counts of B1 lymphocytes (CD19+CD5+)." (PMID 39056769, 2024). "Moreover, CD20+ B cells in ectopic endometrium had significantly elevated CD5 and HLA-DR expression levels compared with the eutopic endometrium in both patients with endometriosis and controls." (PMID 35146127, 2022). "Moreover, increased numbers of CD5+ B1 cells and the FceRIa+ subset were found within the pelvic cavity in patients with endometriosis along with the excessive production of autoantibodies of B1 cells." (PMID 36369244, 2022). "In our study, adolescent patients with endometriosis revealed lower counts of CD16+ monocytes and lower counts of B1 lymphocytes (CD19+CD5+) vs. the comparison group." (PMID 39056769, 2024). "For example, one feature of the eutopic endometrium in women with endometriosis is unusual infiltration of CD138(+) ESPCs and CD20(+)/CD5(+)/HLA-DR(+) B cells; these are typical immunocompetent cells observed in CE, but are sparse in the nonpathological endometrium." (PMID 36359553, 2022).
glioblastoma (4 papers, 2017 to 2025). The most malignant astrocytic tumor (WHO grade IV). "Although it is widely believed that cDC1s are pivotal for anti-tumor responses, there is an argument for further investigation of CD5- cDC2s in glioblastoma, as the significance of these cells may be under appreciated." (PMID 37928547, 2023). "Directly comparing glioblastoma and RRMS patients, higher fractions of CD5+ activated TZB (Bc 11) and CD24+/CD27+ Bregs (Bc 19) were noted in the PB of RRMS patients." (PMID 39497174, 2024).
graft versus host disease (4 papers, 2019 to 2024). An immune system disorder that occurs after allogeneic hematopoietic stem cell transplant and is a reaction of donor immune cells against host tissues. "MSCs can not only directly restrain proliferation of the effector B cells but also induce differentiation of the CD19+CD5+ B cell subset of patients with graft versus host disease, which secretes IL-10, thus being recognized as Bregs." (PMID 34790240, 2021).
sarcoidosis (4 papers, 2016 to 2023). Sarcoidosis is a multisystemic disorder of unknown cause characterized by the formation of immune granulomas in involved organs. "An increased count of CD19 + CD5 + CD27– cells in bronchoalveolar lavage has been previously reported in sarcoidosis, thereby confirming the assumption that Breg cells counteract to suppress inflammatory reactions." (PMID 38179278, 2023). "Next, we demonstrated the increased level of CD5-expressing B cell in peripheral blood of sarcoidosis patients." (PMID 31974463, 2020). "Cluster of Differentiation 72 (CD72) is a CD5 co-ligand involved in hypersensitivity reactions and sarcoidosis, highly expressed in pulmonary alveolar macrophages." (PMID 27814717, 2016). "Moreover, we found that in sarcoidosis patients there are increased levels of B cell subsets, which were previously shown to display regulatory capacities (CD24+++ CD38+++ and CD5 + CD27−)." (PMID 31974463, 2020).
Thrombocytopenia (4 papers, 2016 to 2024). A reduction in the number of circulating thrombocytes. "Haplotypic analyses showed the association of CD5 rs2241002T-rs2229177C haplotype with an increased risk of anemia and thrombocytopenia." (PMID 35372412, 2022). "Logistic regression analysis of CD5 haplotype association to anemia and thrombocytopenia." (PMID 35372412, 2022).
thymic squamous cell carcinoma (4 papers, 2017 to 2022). "All the three TC samples were histologically diagnosed as thymic squamous cell carcinomas with CD5+ and CD117+." (PMID 34568003, 2021). "According to the 4th edition of the WHO classification of tumors of the lung, pleura, thymus and heart, the positive rates of CD5 and CD117 in thymic squamous cell carcinoma are 74% and 84%, respectively." (PMID 28095872, 2017).
thyroid tumor (4 papers, 2018 to 2025). A benign or malignant neoplasm affecting the thyroid gland. "Positive staining with CD5 marker helps to differentiate CASTLE from other tumors of the thyroid, respiratory tract, or upper gastrointestinal tract." (PMID 34399813, 2021). "Immunohistochemical staining with CD5 can help to differentiate thyroid CASTLE from other aggressive thyroid neoplasms." (PMID 31312445, 2019). "Although the immunophenotype of our case indicated epithelioid–squamoid differentiation, the characteristic expression patterns of TTF-1, Pax-8, and CD5 were absent in the thyroid tumor." (PMID 29885658, 2018). "Regarding immunohistochemistry, most ITTC cases were positive for CD5, a marker for carcinoma of thymic origin, as well as for p63, CD117, CK5/6 and negative for thyroid transcription factor 1 (TTF-1), to distinguish it from other thyroid tumors, also described in the literature." (PMID 41278290, 2025).
abortion (3 papers, 2018 to 2021). the ending of pregnancy by removing a fetus or embryo before it can survive outside the uterus. "Furthermore, in our previous work, we have shown that at 14 dpc, abortion-prone mice have an increased proportion of CD19+CD5+CD1dhigh+ cells in the uterine draining lymph nodes when compared to that of mice with healthy pregnancies." (PMID 34298914, 2021). "The frequencies and cell numbers of peritoneal and splenic CD19+IL-10+ and CD19+CD5+IL-10+PC1+ cells were assessed in virgin as well as normal pregnant (NP) and abortion-prone (AP) females during the course of gestation." (PMID 29868008, 2018).
anemia (3 papers, 2015 to 2025). A reduction in the number of red blood cells, the amount of hemoglobin, and/or the volume of packed red blood cells. "Within this cohort, elevated LDH levels (P = 0.015), anemia (P = 0.046), CD5 + (P < 0.001), initial treatment response (P = 0.006), and time to relapse > 12 months from the initiation of R-CHOP (P = 0.001) were identified as adverse prognostic factors affecting OS." (PMID 40418267, 2025). "For GBM, they are elevated LDH, CD5 + expression, time to relapse > 12 m, initial response, age, ALB, B symptoms, and anemia." (PMID 40418267, 2025).
autism (3 papers, 2011 to 2024). Persistent deficits in social interaction and communication and interaction as well as a markedly restricted repertoire of activity and interest as well as repetitive patterns of behavior. "It has previously been observed that children with ASD had significantly higher serum and plasma levels of CD5 than those of normal controls, which is positively correlated with Childhood Autism Rating Scale score." (PMID 38742104, 2024). "Patient CD5 had language delay (LD) and DD during his childhood, and his two sons (CD21 and CD22) displayed absence of speech, DD and autistic disorder." (PMID 24603971, 2014).
breast tumor (3 papers, 2020 to 2024). "We determined CD5 levels in T cell subsets in different organs in mice bearing syngeneic 4T1 breast tumor homografts and assessed the relationship between CD5 and increased T cell activation and effector function by flow cytometry." (PMID 33584650, 2020). "Here we challenged mice with poorly immunogenic 4T1 breast tumour cells and tested whether treatment with anti-CD5 monoclonal antibodies (MAb) in vivo could enhance non-malignant T cell anti-tumour immunity and reduce tumour growth." (PMID 38487537, 2024).
celiac disease (3 papers, 2021 to 2025). An autoimmune genetic disorder with an unknown pattern of inheritance that primarily affects the digestive tract. "IELs in celiac disease and RCD I show downregulated expression of CD5, but they are not entirely CD5-negative, and they may have a mixture of CD5-positive and negative subsets in some cases." (PMID 34830926, 2021).
fungal infection (3 papers, 2015 to 2022). "CD5 has a protective role against fungal infection by recognizing and binding to fungal species via β-glucan, while CD6 recognizes and binds to bacterial LPS." (PMID 34983375, 2022). "Upon stimulation with zymosan (a protein-sugar moiety derived from the yeast cell wall), a CD5-transfected cell line produces IL-8, suggesting that CD5 has a pro-inflammatory role in fungal infection." (PMID 29358941, 2017). "Biopsy results demonstrated CD4 positivity, consistent with Mycosis Fungoides with coexpression of CD5, CD47, and CD7." (PMID 26380134, 2015).
lymphoid neoplasm (3 papers, 2020 to 2025). A neoplasm composed of a lymphocytic cell population which is usually malignant (clonal) by molecular genetic and/or immunophenotypic analysis. "Elevated CD5 is associated with B cell activation and is found to be expressed on certain lymphoid tumors." (PMID 33584650, 2020). "Markers for lymphoid neoplasms (CD3, CD5, and CD20), cyclin D1, and BCL2 were negative, and EBER in situ hybridization was also negative, effectively excluding lymphoid and viral-driven differentials." (PMID 40951125, 2025).
malaria (3 papers, 2018 to 2025). Malaria is a serious and sometimes fatal disease caused by a parasite that commonly infects a certain type of mosquito which feeds on humans. "This is most apparent in the CD5 loop of myzozoan CIA1 proteins, which ranges in length from 45 amino acids in the oyster parasite P. marinus to 313 amino acids in the malaria-causing parasite P. falciparum." (PMID 41289326, 2025). "The percentage of the CD19 + CD5 + TACI+ B cell appeared to be enhanced in malaria patients." (PMID 29314720, 2018).
non-small cell lung carcinoma (3 papers, 2015 to 2022). A group of at least three distinct histological types of lung cancer, including non-small cell squamous cell carcinoma, adenocarcinoma, and large cell carcinoma. "CD5, a T-Cell surface glycoprotein, was mainly expressed on T cells and a small subset of normal B cells and was considered as an immunoregulatory biomarker in resectable non-small cell lung cancer and other cancer types." (PMID 35846149, 2022). "However, CD5 positive is useful for accurate diagnosis because pulmonary squamous cell carcinoma is consistently negative for CD5 by a large study of 1465 non-small cell lung cancer cases." (PMID 27822875, 2016).
psoriasis (3 papers, 2021 to 2023). An autoimmune condition characterized by red, well-delineated plaques with silvery scales that are usually on the extensor surfaces and scalp. "It will be interesting to quantify E-cadherin+Axl+CD5+ cDC2s in the blood of psoriasis and carcinoma patients." (PMID 37539048, 2023). "Moreover, in a mouse model of imiquimod-induced psoriasis, a more severe skin inflammation observed in the CD19−/− mice in comparison to the wild type mice was indicative of the IL-10(+) CD1d(high)CD5(+) Bregs’ role in suppressing the psoriasis-like inflammation." (PMID 33669402, 2021).
T-cell immunodeficiency (3 papers, 2022 to 2024). A broad classification of disorders that affect the cell-mediated aspect of the immune response. "In addition, 12 C CAR-NK cells showed cell lysis properties towards normal autologous and allogeneic T cells due to CD5 expression in normal T cells, indicating that T-cell immunodeficiency would be induced by 12 C CAR-NK cells targeting T cell malignancies." (PMID 39462383, 2024).
type 2 diabetes (3 papers, 2021 to 2024). "We also reported a decreased frequency of regulatory CD19+CD5+CD1dhi cells in T1D than latent autoimmune diabetes in adults and type 2 diabetes." (PMID 34778464, 2021). "We also found decreased B10 cells (IL-10-producing CD19+CD5+CD1dhi) in circulating blood of patients with T1D compared with patients with latent autoimmune diabetes in adults and patients with type 2 diabetes." (PMID 34778464, 2021). "PAK3, CD44, CD5, SOCS3, VAV1, and PIK3CD are negatively correlated with cardiac systolic function, and P2RY1 is positively correlated with LVEF, which may be referred to in studies on type 2 diabetes." (PMID 34925642, 2021).
adult T-cell leukemia (2 papers, 2022 to 2024). "Adult T-cell leukemia/lymphoma (ATLL) cells showed typical irregular nuclear contours and were characterized by moderate CD2, CD4, and CD5, loss of surface CD3, CD7, and CD26, and dim-to-negative CD279." (PMID 35299754, 2022).
atherosclerosis (2 papers, 2021 to 2024). A disease characterized by the build-up of fatty material and calcium deposition in the arterial wall resulting in partial or complete occlusion of the arterial lumen. "Therefore, decreased CD19(+)CD5(−) B cells might be associated with the uremic environment and was correlated with atherosclerosis." (PMID 34844574, 2021). "CD19(+)CD5(+) B cells have been reported to protect from atherosclerosis by the production of IgM antibodies." (PMID 34844574, 2021). "In mouse atherosclerosis, B cells are subdivided into two main subsets, B1 and B2, where B1 cells are divided into CD5+ B1a cells and CD5- B1b cells according to the expression of the leukocyte differentiation antigen CD5, and B2 cells contain follicular (FO) and marginal zone (MZ) B cells." (PMID 39399488, 2024). "CD19(+)CD5(+) B cells may have a protective effect on atherosclerosis that is largely mediated by the production of IgM antibodies." (PMID 34844574, 2021). "Our results showed that decreased CD19(+)CD5(+) and CD19(+)CD5(−) B lymphocytes were correlated with atherosclerosis and worse survival, which indicates that B lymphocytes might involve in atherosclerosis and associated the prognosis of elderly patients with moderate-to-severe CKD." (PMID 34844574, 2021). "Our results showed that the levels of CD19(+)CD5(+) B cells was significantly decreased in moderate-to-severe CKD patients and IMT was increased in the lower levels of CD19(+)CD5(+) B cells, that could explain why patients with CKD exhibit accelerated development of atherosclerosis." (PMID 34844574, 2021).
bacteremia (2 papers, 2016 to 2018). "At times of peak bacteremia, a decrease in eosinophils and lymphocytes, as well as subsets thereof (B lymphocytes and CD5+, CD4+ and CD8+ T lymphocytes), and an increase in monocytes were particularly significant in the passively immunized cats." (PMID 27496124, 2016).
chronic graft versus host disease (2 papers, 2016 to 2017). Chronic graft versus host disease (GVHD) is a complication that can occur after a stem cell or bone marrow transplant in which the newly transplanted donor cells attack the transplant recipient's body. "Patients with refractory chronic graft versus host disease (cGvHD) present lower frequencies of total B cells and CD5+IL-10+ B. However, after three months of MSC treatment patients showed improvement of their symptoms correlating with increased CD5+IL-10+ B cells." (PMID 27956762, 2016).
chronic kidney disease (2 papers, 2024 to 2025). Impairment of the renal function secondary to chronic kidney damage persisting for three or more months. "Furthermore, studies in children with chronic renal failure have demonstrated a reduced population of CD5+ innate B cells and CD27+ memory B cells." (PMID 40276114, 2025).
chronic leukemia (2 papers, 2010 to 2025). A slowly progressing leukemia characterized by a clonal (malignant) proliferation of maturing and mature myeloid cells or mature lymphocytes. "Flow cytometry (chronic leukemia immunophenotyping) revealed CD5 positivity, CD23 positivity, Sm Ig weak positivity, CD22 or CD79b weak, CD10 negativity, and FMC7 negativity." (PMID 40815495, 2025). "Here, we investigated the in vivo therapeutic effects of the two xanthones in a xenograft murine model of human CLL, developed by engrafting CD5-transfected chronic leukemia B cells into SCID mice." (PMID 21138552, 2010).
experimental autoimmune encephalomyelitis (2 papers, 2022 to 2025). An autoimmune demyelinating disease of the central nervous system that is produced experimentally in animals by the injection of homogenized brain or spinal cord in Freund's adjuvant. "This is consistent with the protective effect of CD5 KO previously reported in experimental autoimmune encephalomyelitis (EAE) and associated with increased AICD." (PMID 35720357, 2022).
gastric cancer (2 papers, 2015 to 2023). A primary or metastatic malignant neoplasm involving the stomach. "PBMCs from gastric cancer patients were stained with various combinations of monoclonal antibodies to proteins which have been suggested for use in identifying Bregs, including: CD5, CD1d, CD38, CD24, IgM, CD25, CD10, and CD21." (PMID 26378021, 2015). "Our results demonstrate that CD19+CD24hiCD38hi B cell subsets possess a robust immune regulatory capacity to produce IL-10 in gastric cancer, which is consistent with a previous report in SLE and includes most CD5+CD1dhi B cells." (PMID 26378021, 2015).